DLL4 (delta like canonical Notch ligand 4)
Diseases named in the same sentence as DLL4 in open-access papers (continued):
Sharing a sentence is not in itself a finding about the gene and the disease.
tumor (continued). "Blocking DLL4 signalling using anti-DLL4 antibody effectively delayed tumour growth possibly by disrupting functional angiogenesis, implying that DLL4 is a dominant ligand over JAG1 in tumour angiogenesis and tumour growth." (PMID 28445154, 2017). "Both DLL4 and JAG1 increase vessel perfusion and thus reduce necrosis and enhance tumour growth." (PMID 28445154, 2017). "Targeting DLL4 with an antibody (anti-DLL4 IgG1) yielded robust anti-tumor activity in several nonclinical models, making DLL4 an attractive therapeutic target." (PMID 28475417, 2017). "On the other hand, recombinant ligands such as Dll1, Dll4, and JAG1 have been reported to activate Notch signaling in various cell types, including intestinal organoids and tumor spheroids." (PMID 28455349, 2017). "Therefore, we investigated different effects of DLL4 and JAG1 on in vitro angiogenesis, on xenograft tumour growth and vasculature, and on tumour response to anti-VEGF therapy." (PMID 28445154, 2017). "The inhibition of Delta-like 4 (Dll4)/Notch signaling has been shown to result in excessive, nonfunctional vessel proliferation and significant tumor growth suppression." (PMID 28288569, 2017). "Demcizumab (VS-6063) is a humanized IgG2 anti-DLL4 (delta-like ligand 4) antibody that inhibits tumor growth by suppressing the Notch pathway." (PMID 27938382, 2016). "Conversely, inhibition of Dll-4-Notch increases non-functional vasculature and reduces tumor growth." (PMID 27608016, 2016). "Furthermore, preclinical models indicated that the combination of targeting the Dll4/Notch pathway and anti-VEGF treatment leads to synergistic tumor growth inhibitory effects." (PMID 26755662, 2016). "Conversely, anti-Dll4 antibodies or gamma-secretase inhibitors that block Notch activation induce non-productive hypersprouting and reduce tumour growth." (PMID 25557927, 2015). "Moreover, in endothelial and tumor cells' coculture model, it was shown that the expression of a NOTCH ligand DLL4 (Delta-like ligand 4) in HUVEC endothelial cells increased NOTCH1 and suppressed the proliferation of cocultured A549 and H460 NSCLC cells." (PMID 26491213, 2015). "Blockade of DLL4 was shown to lead to increased nonproductive tumor vasculature inhibiting tumor growth." (PMID 26213336, 2015). "In invasive malignancies, Dll4/Notch signaling inhibition enhances non-functional vessel proliferation and limits tumor growth by reducing its blood perfusion." (PMID 26314892, 2015). "Taken together, DLL4/Notch signaling, which is interconnected with VEGF signaling, is a crucial mediator of endothelium–cancer cell communication in various processes including angiogenesis and tumor metastasis." (PMID 24931473, 2014). "Thus, the combination of DLL4 blockade with USMB and radiation is a novel, highly effective approach to delay tumour growth through biological and biophysical targeting of the tumour vasculature." (PMID 24736631, 2014). "Combination treatment of anti-human and anti-mouse Dll4 antibodies did not result in enhanced anti-tumor effects compared to single agent administration of REGN1035." (PMID 25393540, 2014). "An increased level of Dll4 expression was shown to be an independent prognostic predictor of OS (P=0.021) and PFS (P=0.034) times, in addition to the presence of tumor metastasis (OS, P=0.001), tumor stage, tumor grade (OS, P=0.045) and high expression levels of VEGFR-2." (PMID 25364440, 2014). "In addition, simultaneously targeting Dll4 and VEGF has been shown to generate additive antitumor effects compared with single agents in numerous tumor models." (PMID 25364440, 2014). "Studies have demonstrated that inhibiting Dll4 signalling results in excessive but non-functional angiogenesis in tumour tissue." (PMID 24736631, 2014). "Functional tumor angiogenesis requires a balance of VEGF signaling and Dll4 expression." (PMID 25364440, 2014).
tumor (continued). "DLL4 expression was primarily identified in the membranes and cytoplasm of cancer cells, regardless of tumor histology, as well as infiltrative cells in cancer stroma." (PMID 23898884, 2013). "Then, the expressions of DLL4 and mature miR-30a from 90 cases of ccRCC and 28 cases of nonmatched adjacent non-tumor tissues were measured by quantitative real-time PCR." (PMID 23826258, 2013). "In solid tumors, blocking Dll4 leads to excessive sprouting and “non-productive” angiogenesis, which results in decreased vessel perfusion and inhibition of tumor growth." (PMID 23601498, 2013). "Other groups have shown that antibodies against Dll4 and Notch1 increase non-functional EC vasculature in subcutaneous tumor models." (PMID 24066611, 2013). "Several studies have already reported that the Dll4 blockade inhibits tumor growth by inducing nonproductive angiogenesis manifested by an increased tumor vascular density, but a decreased tissue perfusion." (PMID 23531541, 2013). "Antibody against Dll4, soluble Dll4 or Dll4 vaccination increased non-functional tumor vessel growth and inhibited tumor growth." (PMID 24213317, 2012). "Predictive biomarkers produced by the tumor or expressed within the tumor vessels that confer sensitivity to Dll4-Notch blockade have not yet been identified." (PMID 21923938, 2011). "Dll4 expression by BM-VPC may therefore be considered as an important regulator of vessel stabilization, essential for tumor angiogenesis but also in other vascular pathologies." (PMID 21483741, 2011). "Dll4 expression was generally not observed in the tumor parenchyma, although sporadic tumor cell expression was detected in colorectal and brain tumor samples." (PMID 21923938, 2011). "Studies in humans and mice have demonstrated that Dll4 is strongly expressed by the tumor vasculature and generally not by the tumor cells themselves." (PMID 21923938, 2011). "Blockade of Dll4-Notch signaling in tumors results in excessive, non-productive angiogenesis with resultant inhibitory effects on tumor growth, even in some tumors that are resistant to anti-VEGF therapies." (PMID 21923938, 2011). "Dll4 is strongly upregulated in tumor endothelium compared to normal organs, however it is expressed to some degree in smaller arteries and capillaries of normal tissues, as well as in the thymic stroma and the gastrointestinal tract." (PMID 21923938, 2011). "We now have a fairly detailed understanding of the mechanism of action for how disrupting DLL4-Notch signaling leads to non-functional vasculature and thereby reduces tumor growth." (PMID 21831306, 2011). "While most of the current anti-angiogensis approaches act through a reduction or elimination of tumor blood vessels, DLL4 blockade results in the formation of a non-functional vasculature incapable of supporting tumor growth." (PMID 21824400, 2011). "Furthermore, the simultaneous targeting of Dll4 and VEGF has produced additive anti-tumor effects compared to single agents in a number of tumor models (; Kirshner and Thurston, unpublished)." (PMID 21923938, 2011). "Blockade of Dll4-Notch signaling in tumors results in excessive, non-productive angiogenesis and inhibitory effects on tumor growth." (PMID 21923938, 2011). "Similarly, strong expression of Dll4 on the growing front of tumor vessels and VEGF regulation of Dll4 in tumors has been documented." (PMID 21923938, 2011). "A putative role for BM-VPC in the setting of Notch:Dll4 signaling during tumor angiogenesis has not been studied and was the subject of the present report." (PMID 21483741, 2011). "Perfusion studies demonstrated that the hypersprouting tumor vasculature was non-functional and consequently, anti-Dll4-treated tumors exhibited increased levels of hypoxia." (PMID 21923938, 2011). "Average tumor numbers per mouse were similar in RT2 Dll4+/+ and RT2 Dll4+/- littermates." (PMID 21092311, 2010).
tumor (continued). "Whereas most of current antiangiogenesis approaches act through the reduction or elimination of tumor blood vessels, Dll4 blockade results in the formation of a nonfunctional vasculature that is unable to support tumor growth." (PMID 20414463, 2010). "To examine whether synchronous suppression of Dll4/Notch and EphB4/Ephrin-B2 signaling pathways might result in greater inhibition of RT2 tumor development, we treated RT2 Dll4+/- mice with sEphB4-Alb." (PMID 21092311, 2010). "In addition, subgroups of RT2 Dll4+/+ and RT2 Dll4+/- mice were perfused with endothelium-binding lectin to visualize the perfused regions of the tumor vasculature." (PMID 21092311, 2010). "Current findings suggest that angiogenic sprouting in the tumor is tightly controlled by positive and negative regulation of Jagged1 and Dll4 in both endothelial and non-endothelial cells." (PMID 20016694, 2009). "The key receptor–ligand pair in tumour endothelium appears to be delta-like ligand-4 (DLL4) and Notch-1." (PMID 19002176, 2009). "Remarkably, the inhibition of Dll4-Notch signaling increased neovascularization but impaired tumor growth, because the non-productive angiogenesis reduced tumor perfusion." (PMID 20016694, 2009). "The striking pattern of Dll4 expression in tumour vessels prompted several groups to target Dll4-Notch activity and provided insight into a role for Dll4-Notch in regulating VEGF-induced vascular sprouting." (PMID 18827808, 2008). "More importantly, we identified DLL4/Notch and JAG/Notch signaling as the key ligand-receptor pairs involved in ligand‒receptor interactions in ccRCC, which might disrupt angiogenesis to reduce tumor growth and metastasis." (PMID 40535574, 2025). "Repression of endothelial Snai1-expression in the strongly pro-angiogenic tumor microenvironment has the opposite effect, reducing the ill-fated excessive sprouting via increased Notch1/Dll4 expression, leading to stable vessels that are no longer prone to constant remodeling and degradation." (PMID 39095583, 2024). "The increased formation of non-productive angiogenesis could be induced by blocking DLL4; this process showed its anti-tumor potential." (PMID 34638298, 2021). "Although blocking a pathway that is known to serve as an angiogenic “off switch” seems counterintuitive, agents targeting DLL4 have been shown to reduce tumor growth in vivo by promoting disorganized and non-productive endothelial sprouting and poor tumor perfusion." (PMID 34926282, 2021). "To test whether the downregulation of EGFR in tumor spheres was dependent on the activation of Notch1, we performed binding assays of parental cells (H1975 and HCC827) to plates coated with an increasing concentration of the DLL4 Notch agonist." (PMID 33922104, 2021). "In addition, blocking the DLL4/Notch1 interaction in cancer is being explored in clinical trials because DLL4 inhibition has been shown to cause non-productive vessel formation within the TME, thereby inhibiting tumor growth." (PMID 33681228, 2021). "Moreover, no TNPs were detected from 0-15 μm from CD31- or DLL4-stained blood vessels in SSIL2Rγ- tumor sections (inset)." (PMID 32373218, 2020). "Using RBPj-Notch reporter activation as an indicator for Notch activation and combining with specific Notch receptor antagonists, it was found that this effect proceeded from endothelial Dll4 signaling through Notch1, but not Notch3, in neighboring tumor cells." (PMID 33198378, 2020). "Overall, this study indicates a low frequency of the circulating antitumor Th1 subset in IBC and suggests that tumor Syndecan-1 silencing enhances ex vivo polarization of CD4+ Th17 and Treg cells of non-IBC, whereby Th17 polarization is possibly mediated via upregulation of IL-23 and DLL4." (PMID 31145753, 2019).
tumor (continued). "Expression of Notch receptors and ligands continue to be present in mature vessels to maintain vascular integrity and homeostasis, whereas inhibition of DLL4/Notch signaling enhances non-functional vessel growth and significantly limits tumor growth by reducing blood perfusion in lung malignancies." (PMID 31739580, 2019). "Furthermore, in tumor models, blockade of Dll4-Notch signaling results in vessel hypersprouting, nonfunctional tumor vasculature, and inhibition of tumor growth." (PMID 29996493, 2018). "The appearance of abnormal vessels and the insufficient tumor growth are also related to the correlation between the Dll-4 expression and the VEGF molecule in “tip” and “stalk” cell; blockade of the VEGF action on neoplastic structure downregulates Dll-4 expression." (PMID 30111989, 2018). "However, whether there is any function interaction between DLL4 and JAG and how such an interaction would affect tumour angiogenesis and tumour growth and progression are unknown." (PMID 28445154, 2017). "We generated RT2 Tie2-rtTA-M2 TetO7-Dll4 mice and simulated a therapeutic intervention by inducing endothelial Dll4 overexpression in a mouse group (RT2 D4OE) vs. non-induced control group (RT2 D4BE) (n = 10) during the developing RT2 tumor stage (10 – 13.5 weeks old animals)." (PMID 28288569, 2017). "At the start of the anti-DLL4 development program, the hypothesis was that the DLL4 pathway was only active in tumor, rather than normal vasculature, and that the effects would be similar to the approved angiogenesis inhibitor, bevacizumab (Avastin®)." (PMID 28475417, 2017). "Given the central role of the Wnt signaling in ApcMin/+ tumorigenesis, we measured the tumor density of the Wnt pathway-derived non-phosphorylated (active) β-catenin to understand if Dll4 ubiquitous and/or endothelial-specific inhibition was affecting this pathway." (PMID 28086833, 2017). "JAG1 is not antagonistic but utilises DLL4 in tumour angiogenesis." (PMID 28445154, 2017). "To confirm that the findings of DLL4 down-regulation in cancer cell lines was not just a genetic phenomenon restricted only to the cell lines, we analyzed the DLL4 protein level in normal and cancer patients’ tumor tissues by immunohistochemistry (IHC)." (PMID 27542210, 2016). "The tumor inhibition rate was evaluated, followed by the quantification of messenger ribonucleic acid (mRNA) and protein expression of notch signaling components NOTCH-1, NOTCH-3, NOTCH-4, JAG-1, DLL-4, Hes-1, and Hey-1 using quantitative polymerase chain reaction (qPCR)." (PMID 26762567, 2016). "Based on the crucial role of Dll4/Notch signaling in the vascular sprouting and tumor angiogenesis, pharmacological targeting of the Dll4/Notch has been shown to be effective as a novel anti-angiogenic therapy by blocking non-productive vessel growth and tumor collapse." (PMID 26713603, 2016). "Also when combined with ionizing radiation, Dll4 blockade impaired the tumor growth by promoting non-functional tumor angiogenesis." (PMID 26713603, 2016). "Emerging new approaches that target the Notch signaling ligand DLL4 result in excessive non-productive angiogenesis, affecting both tumor growth and metastatic behavior in tumors that are refractive to anti-VEGF therapies, although off-target effects are possible." (PMID 25512384, 2015). "However, a tumour growth delay similar to radiation alone was observed, indicating that Dll4 mAb based vascular shutdown is not sufficient to induce substantial tumour damage." (PMID 24736631, 2014). "Moreover, tumor growth was further inhibited when the vascular endothelial growth factor inhibitor bevacizumab was added to this treatment regimen suggesting synergy between anti-VEGF treatment and Dll4 targeting." (PMID 25366565, 2014). "In the case of Dll4 inhibition, the newly formed tumor vascular structures are non-functional." (PMID 23238831, 2013).
tumor (continued). "Notably, although Dll4 has been demonstrated to be a key regulator in tumor angiogenesis, β-elemene failed to influence its expression in our study." (PMID 23710217, 2013). "Perfusion studies demonstrated that hypersprouting tumor vasculature was non-functional, which suggested that blockade of DLL4-Notch signaling could lead to tumor vessel “abnormalization” and inhibited tumor growth." (PMID 23028940, 2012). "Delta-like 4 (Dll4) is a ligand of the Notch pathway family which has been widely studied in the context of tumor angiogenesis, its blockade shown to result in non-productive angiogenesis and halted tumor growth." (PMID 23285048, 2012). "In tumors targeted by DLL4/NOTCH1 inhibition, the hyperproliferative state of endothelial cells, together with the reduced protection of the tumor endothelium by supporting cells, may render the tumor vasculature more susceptible to agents that selectively target proliferating cells." (PMID 21824400, 2011). "Interestingly, although most colorectal and breast tumors showed positive Dll4 expression in tumor vessels, some tumors were negative." (PMID 21923938, 2011). "Similarly, blockade of EphrinB2 signaling with soluble EphB4-Albumin resulted in reduced tumor vascularization in the RIP1-Tag2 model of pancreatic islet carcinogenesis, consistent with an inhibitory activity on VEGF signaling and a function upstream of Dll4." (PMID 21923938, 2011). "In contrast, Dll4 haploinsufficiency and intermittent administration of sDll4 (3 times a week for 3.5 weeks) in RT2 mice significantly reduced tumor growth, but did not cause any vascular lesions in the liver or other vital organs such as heart, brain, lung, kidney, and intestine (data not shown)." (PMID 21092311, 2010). "Importantly, the Notch decoy reduces tumor growth without increasing vessel growth, which suggests that the effects of the Notch decoy differ from those induced by Dll4 blockade." (PMID 20016694, 2009). "This study suggests that tumour endothelial expression of Dll4 may not be a significant prognostic factor, but is significantly associated with VEGF expression." (PMID 19844231, 2009). "If EERAC could affect CRC through Notch/DLL4 influencing tumor angiogenesis has not been reported." (PMID 34476005, 2021). "Tumor regression was similar in SS.BN3IL2Rγ- rats whether treated by anti-DLL4-conjugated TNPs or IgG-conjugated TNPs followed by PTT, however, strong differences in TGI were observed in SSIL2Rγ- (DLL4-high strain) rats when treated by DLL4-conjugated TNPs vs control IgG-TNPs." (PMID 32373218, 2020). "Notably, DLL4 is a master regulator of angiogenic vascular patterning 27-35 and inhibition of DLL4 attenuates tumor growth and progression by eliciting nonproductive angiogenesis 28, 31-35, yet the explicit role of DLL4 in EPR and its influence on NP delivery and efficacy remains untested." (PMID 32373218, 2020). "Such a potent increase in tumor cell apoptosis by the combination treatment might be due to direct cytotoxic effects of irinotecan against highly proliferating tumor cells together with the anti-angiogenic effects of mABL001, a bispecific antibody binding against dual antigens, VEGF, and mouse DLL4." (PMID 33383646, 2020). "Therefore, we decided to elucidate if Dll4 inhibition could be effective in blocking ApcMin/+ tumor initiation and development through angiogenic and/or non-angiogenic mechanisms." (PMID 28086833, 2017). "In 370 HCC samples, the expression levels of Notch 1, Notch 2, Notch 3, Notch 4, DLL4, JAG1, and JAG2 were markedly greater in tumor samples compared to surrounding non-tumorous tissue." (PMID 38816668, 2024). "Cetuximab treatment typically results in reduced angiogenesis or vascularization of the tumours (compare to Section 4), which points to another link to Notch signalling, in particular the NOTCH4/DLL4 axis." (PMID 34944837, 2021).